IL6 (interleukin 6)
Diseases named in the same sentence as IL6 in open-access papers (continued):
Sharing a sentence is not in itself a finding about the gene and the disease.
Sepsis (continued). "Because inflammation contributes to cardiac dysfunction during sepsis, TNF-α and IL-6 mRNA levels in the myocardium were assessed by real-time PCR 6 hours following LPS administration in APN-KO and WT mice." (PMID 25180179, 2014). "A correlation between presepsin and inflammatory biomarkers, such as CRP, WBC, IL-6 and PCT, can be explained by the ongoing systemic activation of inflammatory biomarkers during severe sepsis and septic shock." (PMID 25190134, 2014). "Endotoxin mediated septicemia often involve excessive inflammation mediated by several inflammatory genes including COX-2, TNF-α, IL-12 and IL-6." (PMID 25428720, 2014). "Hence ACVR2A may affect sepsis processes by regulatingthe levels of IL-6 or TGF-β." (PMID 24303815, 2014). "Further, neuroimmunopathogenesis of sepsis involves peripheral release of proinflammatory cytokines (TNF-α, IL-1α, IL-1β, and IL-6) increasing blood brain barrier (BBB) permeability, generating neuroinflammation and sepsis associated sickness behaviour." (PMID 25018890, 2014). "Blood samples were collected at the time that severe sepsis was diagnosed to determine serum levels of CCCK-18, tumor necrosis factor (TNF)-alpha, interleukin (IL)-6 and IL-10." (PMID 25290885, 2014). "Female patients with sepsis had a higher survival rate, which was correlated with lower TNF-α and higher IL-10 levels, while male trauma-patients showed higher IL-6 level than females." (PMID 24945834, 2014). "Sepsis patients with higher numbers of circulating interphase neutrophil MDSC had more severe disease, higher concentrations of plasma IL-6 and slower recovery of T cell zeta-chain expression." (PMID 25084831, 2014). "It was identified less than one decade ago in patients with sepsis and appears to be superior to other biomarkers (IL-6 and PCT), as well as to infection site and blood culture, for the diagnosis of severe sepsis of bacterial origin." (PMID 24393424, 2014). "During sepsis, pro-inflammatory cytokines, including tumor necrosis factor (TNF)-α, interleukin (IL)-6 and IL-17, are markedly upregulated." (PMID 24913772, 2014). "When insulin was injected at 4.8 mU · kg-1 · min-1 for 6 h, IL-6 and MDA levels decreased significantly in all brain regions (vs. sepsis group, p < 0.05)." (PMID 25093012, 2014). "As a result, overstimulated macrophages release large amounts of TNF-alpha, IL-1, and IL-6, which lead to the systemic inflammatory response syndrome (SIRS), sepsis, multiple organ failure, and/or death." (PMID 24511409, 2014). "In a study by our group using an LPS-induced DIC model (sepsis DIC model), the administration of immunoglobulin inhibited the inflammatory cytokines TNF and interleukin-6 (IL-6), and coagulation and pathological thrombus formation were suppressed." (PMID 25520834, 2014). "At day 3 of ICU treatment, the diagnostic value of presepsin (AUC = 0.84) to diagnose at least sepsis was significantly better than that of PCT (AUC = 0.69) (AUC difference, P = 0.05) and comparable to that of IL-6 (AUC = 0.81) (AUC difference, P >0.05)." (PMID 25190134, 2014). "Most recently, multicenter clinical studies reported that presepsin is the most valuable predictive marker of sepsis between PCT and IL-6, and is superior to blood culture." (PMID 24443891, 2014). "In vivo models of sepsis have demonstrated that pretreatment with sevoflurane decreased TNF-α and IL-6." (PMID 23552565, 2013). "ROC analyses were performed to compare the diagnostic performance of four clinical parameters of their predictive potential for sepsis: IG#, CRP, LBP and IL-6." (PMID 23398965, 2013). "LPS infusion induced a systemic inflammatory response similar to that encountered during the very early stages of sepsis, with fever, increased heart rate, tachypnoea and hyperventilation, leukocytosis, as well as elevated TNF-α and IL-6 levels." (PMID 24131656, 2013).
Sepsis (continued). "The relative small sample size is a limitation of our study, but the dose-dependent effects of BHT on both the survival rate and circulating IL-6 and IL-10 still provide evidence of BHT as a new treatment option for sepsis." (PMID 23762108, 2013). "It has been shown that systemic proinflammatory cytokines have a central role in sepsis; we investigated next the effects of PD on CLP-induced systemic TNF-α and IL-6 production." (PMID 23431240, 2013). "In acute injuries and diseases such as burns, surgeries, and sepsis, the contents of TNF-α, IL-1β, and IL-6 significantly increase." (PMID 23586067, 2013). "It is triggered by cytokines IL-6, TNF-α, and so forth and is a late marker of neonatal sepsis which increases evidently at 24 h after sepsis onset." (PMID 23984377, 2013). "Induction of IL-19 occurs in severe sepsis and postcardiopulmonary bypass patients with a parallel shift that corresponds to the changes in TNF-α and IL-6." (PMID 23710200, 2013). "Markers such as interleukin-6 (IL-6), C-reactive protein (CRP) and lipopolysaccharide binding protein (LBP) have been proposed for diagnosing or monitoring sepsis." (PMID 23398965, 2013). "To confirm if suppressing inflammatory responses in sepsis by CORM-2 was partly through interruption of the cycle of inflammatory events, we investigated the expression of inflammatory cytokines TNF-α and IL-6 in serum of the septic mice." (PMID 24116078, 2013). "Our data highlight the difficulty of the study of sepsis-induced AKI due to a failure of traditional (BUN, serum creatinine) and emerging biomarkers (urine IL-6, urine NGAL), to accurately reflect the severity of kidney function decline." (PMID 24265742, 2013). "Anti-PD-L1 antibody administration prevented sepsis-induced depletion of lymphocytes, increased tumor necrosis factor (TNF)-α and interleukin (IL)-6 productions, decreased IL-10 production, and enhanced bacterial clearance." (PMID 24324295, 2013). "At the time of diagnosis, serum IL-1beta, IL-6, IL-8, and TNF-alpha levels of culture-proven sepsis were significantly higher than those of the control groups (P<.05)." (PMID 23869218, 2013). "A number of inflammatory cytokines, including IL-6, IL-10, IL-1, and TNF-α were involved in sepsis, which contributes to tissue and organ damage." (PMID 24324295, 2013). "Compound 6e with a statistically significant improved effect on reduction of IL-6 and TNF-α secretion upon E. coli inoculation as compared to ketamine is a good candidate for the treatment of sepsis." (PMID 22664467, 2012). "A hypodynamic state of sepsis in humans can occur in cases of hypovolemia or cardiac depression due to cytokines (tumor necrosis factor (TNF)-α, interleukin (IL)-1β, IL-6, and others)." (PMID 22587828, 2012). "In our study, treatment of myrrh reduced expression of IL-1β, IL-6, and TNF-α in serum and liver during CLP-induced sepsis." (PMID 21826187, 2012). "Serum T3 was negatively and more strongly correlated with IL-6 (r= -0.49, p= 0.001) and CRP (r=- 0.33,p= 0.03) at the 2nd week, at which time sepsis frequency and low T3 rates were the highest." (PMID 22672862, 2012). "On admission, neonates with sepsis had a higher WBC count, IL-6, PCT, and hs-CRP levels compared with those neonates without sepsis." (PMID 22708043, 2012). "Furthermore, a recent study showed that polymicrobial sepsis greatly induced generation of inflammatory mediators in hearts, and CMs isolated from septic rodents spontaneously secreted cytokines and chemokines (IL-6, TNF-α, IL-1β, MIP-1α, MIP-2, MCP-1, KC, and IL-10) in a time-dependent manner." (PMID 23233853, 2012). "More importantly, IL-6 appears to be one of the best predictors to determine MODS, sepsis severity and mortality in both animal models and human." (PMID 23137350, 2012). "IL-6, TNF-α and other inflammatory cytokines are of fundamental importance in sepsis development by mediating some biological responses, such as elevated production of nitric oxide (NO) by macrophages." (PMID 23137350, 2012).
Sepsis (continued). "The observation that BAL levels of IL-6 were increased in septic animals of both genotypes while serum levels of IL-6 were elevated only in septic control mice raises the important question of how intestinal Mttp deletion might influence serum IL-6 kinetics in the setting of sepsis." (PMID 23145105, 2012). "As sepsis progresses, complement activation by considerable release of cytokines (TNF-α, IL-6, IL-10, etc.)produced enormous components, such as C3a, C4a, and C5a, and further consumed the pool of complement C3 and C4." (PMID 23091606, 2012). "Sepsis starts as a process of system inflammation mediated by pro-inflammatory cytokines/chemokines including TNF-α, IL-1, IL-6, MIP-1α, MCP-1, IFN-γ, and IL-17 as well as anti-inflammatory cytokines, e.g. IL-10." (PMID 23056325, 2012). "In CLP mice, levels of pro-inflammatory factors IL-6 and TNF-alpha were significantly increased, while the anti-inflammatory factor IL-10 was decreased in sepsis in both the plasma and peritoneal cavity 24 h after surgery." (PMID 22590504, 2012). "CRP, PCT, IL-6 and LBP levels were significantly higher in patients with sepsis as compared to SIRS." (PMID 21687569, 2011). "In sepsis patients, the KT ratio correlated with plasma IFN-γ (rs = 0.44, p = 0.0002), IL6 (rs = 0.49, p<0.0001) and IL10 (rs = 0.62, p<0.0001)." (PMID 21731667, 2011). "The objective of this prospective single centre cohort study was to see if PCT, IL-6, and LBP are useful in differentiating between sepsis and SIRS in critically ill patients." (PMID 21687569, 2011). "In sepsis patients in our study, IFN-γ concentration correlated with the KT ratio only at baseline, whereas IL6 and IL10 correlated with the KT ratio both at baseline and longitudinally." (PMID 21731667, 2011). "This study showed that PCT levels are of value in differentiating between sepsis and SIRS in critically ill patients and more helpful than CRP, IL-6, or LBP levels." (PMID 21687569, 2011). "To compare the usefulness of CRP, PCT, IL-6, and LBP in differentiating sepsis from SIRS we used the highest level of each in the first 24 hours of admission." (PMID 21687569, 2011). "On admission CRP, PCT, IL-6, and LBP levels were all significantly higher in patients with sepsis in comparison to patients with SIRS." (PMID 21687569, 2011). "In this study, we showed that OMVs derived from intestinal E. coli are causative microbial signals in the pathogenesis of systemic inflammatory response syndrome (SIRS) and sepsis-induced lethality, through the systemic induction of TNF-α and IL-6." (PMID 20596524, 2010). "In our study, IL-6 and 10, the NI, and lactate increased with MOSF and nutritional indices decreased, but only sepsis and IL-10 among the stress mediators were independently associated with the development of MOSF." (PMID 20490277, 2010). "Anti-PD-L1 antibody administration prevented sepsis-induced depletion of lymphocytes, increased tumor necrosis factor (TNF)-α and interleukin (IL)-6 production, decreased IL-10 production, and enhanced bacterial clearance." (PMID 21118528, 2010). "• Anti-PD-L1 antibody administration prevented sepsis-induced depletion of lymphocytes, increased TNF-α and IL-6 production, decreased IL-10 production, and enhanced bacterial clearance." (PMID 21118528, 2010). "In the presence of SIRS or sepsis, CRP, IL-6, IL-10, Prognostic Inflammatory and Nutritional Index (NI), and triglycerides—but not glucose, VO2, or VCO2 increased significantly." (PMID 20490277, 2010). "Serum leptin increases in SIRS and sepsis and is strongly related to circulating levels of TNF-α, IL-6." (PMID 20230641, 2010). "On the second day of ICU admission, significant elevation of leptin, IL-6 and TNF-α occurred in the SIRS and sepsis groups." (PMID 20230641, 2010). "Whereas other studies have demonstrated that increased serum IL-6 predicts subsequent AKI, these studies were conducted in critically ill patients with severe sepsis and acute lung injury." (PMID 19570208, 2009).
Sepsis (continued). "Rodents subjected to stimuli that are known to induce a high intracellular level of HSPs and subsequent induction of otherwise lethal sepsis exhibited attenuated release of TNF-α and IL-6 and reduced mortality." (PMID 19173710, 2009). "This is accompanied by a reduction in the pro-inflammatory mediators IL-1β, IL-6 and TNF-α, as well as a decrease in NF-kB binding activity, thereby inhibiting an overwhelming inflammation response to sepsis." (PMID 19196475, 2009). "In our study, the changes in the systemic levels of IL-6, IL-1-beta, IL-10, and CRP were unable to discriminate survivors from non survivors during the first week of severe sepsis." (PMID 19718443, 2009). "A serial estimation of IL-6 and TNF-α and their correlation with mortality in sepsis were done in elderly patients." (PMID 19881187, 2009). "Thus, this may provide a target to specifically dampen the effects of IL-6 on glia after sepsis." (PMID 19284588, 2009). "Serial estimation of Interleukin-6 (IL-6) and Tumor Necrosis Factor-Alpha (TNF-α) and their correlation with mortality in sepsis in elderly patients and to determine the influence of gender on cytokine production and mortality in elderly patients with sepsis." (PMID 19881187, 2009). "In addition, because NSAIDs have been found to increase inflammatory cytokine production in animal and human studies, and because the mortality rate for sepsis correlates with high interleukin-6 and tumour necrosis factor-α levels, the use of prostaglandin inhibitors in sepsis may be harmful." (PMID 19331665, 2009). "TNF-α and IL-6 were estimated in 30 elderly patients admitted to our intensive care unit with SIRS and sepsis." (PMID 19881187, 2009). "The aim of this study was to determine the value of serum levels of IL-6, IL-8 and C-reactive protein (CRP) as predictors for sepsis or prolonged fever in children with fever and neutropenia due to chemotherapy at the start of a febrile episode." (PMID 18321393, 2008). "Infusion of site-inactivated factor VIIa reduced production of cytokines, including IL-6, IL-8 and soluble TNF (tumor necrosis factor) receptor 1 in a baboon model of sepsis." (PMID 17450221, 2007). "Theaim of this study is to determine serum IL-1β, IL-6, IL-8, and TNF-α levels inneonatal sepsis at the time of diagnosis and after therapy and to show themeaningful on the follow up." (PMID 18274637, 2007). "Following coculture with donor, CP and sepsis PBMC, a significant increase of IL-6 levels in cell culture supernatants was observed (by 553%, 531% and 124%, with p < 0.0001, p < 0.0001 and p = 0.007, respectively)." (PMID 18053242, 2007). "Sepsis and endotoxin activate monocytes, macrophages,lymphocytes, fibroblasts, and endothelial cells that produce and secrete IL-1, TNF-α,α-interferon, IL-6, IL-8, and other proinflammatory cytokines." (PMID 18274637, 2007). "It confirms the notion that plasma levels of IL-6, KC, MIP-2, and TNF soluble receptor I (sTNFR-I) were reliable predictors of lethal outcome in experimental, or clinical sepsis." (PMID 17987129, 2007). "Elevated serum IL-1β, IL-6, IL-8, and TNF-α levels have beenfound in both the neonatal and adult sepsis." (PMID 18274637, 2007). "It has been shown that both IL-6 and PCT are useful markers for diagnosis of sepsis." (PMID 41334533, 2026). "Early sepsis disease 12 h post-infection was characterized by cytokine storm, with concentrations of IFN-γ, CCL2, IL-6, IL-17A, IL-1α, IL-10 and M-CSF significantly elevated in multiple tissues up to 7 days post-infection when mice had recovered from objective clinical measures of disease." (PMID 41910926, 2026). "Consistent with our in vivo sepsis lung tissue data, Fer-1 significantly attenuated LPS induced expression of proinflammatory cytokines IL-1β and IL-6, but not TNFα, as well as the chemokine CXCL1 and chemokine receptor CCR5." (PMID 41518848, 2026).
Sepsis (continued). "In lipopolysaccharide (LPS)-induced sepsis models among animals, exogenous administration of LPA or LPA receptor agonism suppresses the release of proinflammatory factors, including interleukin-6 (IL-6), tumor necrosis factor-alpha (TNF-α), and monocyte chemoattractant protein-1 (MCP-1)." (PMID 41567194, 2025). "Sepsis triggers a systemic inflammatory response syndrome (SIRS), characterized by the release of pro-inflammatory cytokines such as tumor necrosis factor-alpha (TNF-α), interleukin-6 (IL-6), and interleukin-1β (IL-1β)." (PMID 41425961, 2025). "Similarly, sepsis involves massive pro-inflammatory cytokine release (e.g., TNF-α, IL-1β, IL-6), triggering systemic inflammatory responses and tissue injury." (PMID 40657502, 2025). "Four studies reported interleukin-6 levels, showing that the combination of THCQ and CT had some advantage in reducing IL-6 levels in sepsis patients, with a statistically significant difference (MD = −33.55 pg/mL, 95% CI: −52.77 to −14.33; four trials, 301 participants, I2 = 93%)." (PMID 40963685, 2025). "Janus kinase signal transducer and activator of transcription (JAK/STAT) pathway is a critical cellular signal transduction pathway and an important pathway for cytokine signal transduction in the pathogenesis of sepsis, such as tumor necrosis factor-α (TNF-α) and interleukin-6 (IL-6), among others." (PMID 40338919, 2025). "In the emergency departments, IL-6 was an independent predictor of sepsis but did not significantly predict 28-day mortality, in contrast to SOFA score, age, and lactate levels." (PMID 41300951, 2025). "Our study identified higher IL-6 concentrations in sepsis, most notably of non-pulmonary origin, as well as a positive effect of IL-6 on HA at T0 in all groups." (PMID 40512747, 2025). "Notably, studies have shown that increased plasma IL-6 and TNF-α levels in sepsis patients are correlated with mortality." (PMID 40496000, 2025). "CS and IL-6 related signaling pathways transduction are considered as crucial factors involved in sepsis, such as upregulation of IL-6/JAK/STAT3 signaling promotes the progression of sepsis, involvement of IL-6 signaling pathway in the pathogenesis of MOF and other hyperinflammatory diseases." (PMID 39891057, 2025). "Furthermore, the MIF inhibitor also mitigated the effects of CSN6 on the mRNA expression levels of pro-inflammatory cytokines IL-1β, IL-6, TNF-α, and collagen I/III in macrophages in an in vitro sepsis model (n = 6 per group)." (PMID 40595050, 2025). "An initial examination of titles led to the exclusion of 8149 duplicates and 12,931 studies with other research aims (not evaluating the prognostic value of IL-6 in sepsis)." (PMID 40149943, 2025). "For differentiating sepsis from non-sepsis in ICU patients, IL-8, ACSL4, GPX4, CRP, PCT, NEU%, IL-6, and PTGS2(p-value =0.007) exhibited significant diagnostic value (all p-value <0.00001)." (PMID 40264754, 2025). "Furthermore, several studies incorporated within the present meta-analysis assessed the collective predictive capacity of miRNAs, IL-6, PCT, CRP, SOFA score, and additional markers for sepsis mortality." (PMID 40135054, 2025). "After the same IL‐6/LPS stimulation as above, the protein expression and ELISA results confirmed that the pore‐forming activity of GSDMD promoted the release of Gremlin‐1 and VEGF‐B from hepatocytes in sepsis." (PMID 40856013, 2025). "Furthermore, coincubation of OLA@MΦ NPs released from the capsules with IL‐1β, IL‐6, TNF‐α, and LPS, key mediators of the cytokine storm during sepsis, showed dose‐dependent binding of the NPs to these cytokines." (PMID 39836501, 2025). "Studies have shown that ursolic acid may prevent sepsis–induced acute kidney injury in mice by inhibiting reactive oxygen species and inflammatory cytokines in the kidneys, including TNF–α, IL–1β, and IL–6." (PMID 40005889, 2025).